ANGPTL4 (angiopoietin like 4)
Diseases named in the same sentence as ANGPTL4 in open-access papers (continued):
Sharing a sentence is not in itself a finding about the gene and the disease.
tumor (257 papers, 2005 to 2026). "Within the tumor microenvironment, cancer-associated fibroblasts (CAFs) secrete ANGPTL4, which binds to IQGAP1 to activate RAS–ERK signaling." (PMID 40723247, 2025). "While loss of ANGPTL4 in 786O ccRCC cells increased soft agar colony formation in vitro and increased lysosomal acid lipase activity, it decreased in vivo tumor growth, as did treatment of mice with an antibody targeting cANGPTL4." (PMID 40723247, 2025). "ANGPTL4, expressed by ECs, has been associated with tumor angiogenesis and metastasis, whereas SDC4, expressed by cancer cells, is upregulated in GC and linked to invasion." (PMID 41154806, 2025). "In fact, loss of ANGPTL4 increases soft agar colony formation of ccRCC cell lines in vitro and tumor growth in vivo." (PMID 40723247, 2025). "Elevated levels of methylated CpG sites in the angiopoietin-like 4 (ANGPTL4) promoter, which are strongly linked to advanced tumor stage, lead to ANGPTL4 deregulation in HCC." (PMID 38997297, 2024). "Mechanistically, the ADSCs-activated TGF-β1/SMAD3 signaling pathway transcriptionally upregulates the expression of ANGPTL4, which endows tumor cells with an invasive phenotype and is associated with a poor prognosis in CRC patients." (PMID 38643448, 2024). "While in the 786O tumor model, loss of ANGPTL4 or treatment with anti-cANGPTL4 antibodies had the opposite effect, reducing tumor growth." (PMID 39105498, 2024). "This is supported by data showing that loss of ANGPTL4 in CAKi-1 tumors reduced angiogenesis, despite there being an increase in tumor growth." (PMID 39105498, 2024). "As cANGPTL4 is known to promote angiogenesis, we next checked to see if loss of ANGPTL4 affects the tumor vasculature." (PMID 39105498, 2024). "Other reports also show that ANGPTL4 has been linked to tumor progression via directly promoting tumor cell metastasis or modification of vasculature." (PMID 37649607, 2023). "ANGPTL4 has been associated with tumor metastasis by modulating the integrity of vascular EC layers." (PMID 38086791, 2023). "In this study, ANGPTL4 was a high-risk gene that increased with tumor progression, suggesting a reduced survival rate and poor prognosis in LUAD patients." (PMID 36447119, 2023). "ANGPTL4 is secreted by multiple cell types in the tumor microenvironment, including adipocytes and cancer-associated fibroblasts, and is associated with a poor prognosis in breast, gallbladder, and OvCas." (PMID 36795484, 2023). "How ANGPTL4 to mediate the association between ferroptosis and tumour radioresistance under hypoxic microenvironment was further investigated." (PMID 36050447, 2022). "ANGPTL4 is inextricably linked with angiogenesis and also participates in various steps of inflammation and tumour development through autocrine and paracrine forms." (PMID 36050447, 2022). "They found that these factors activate the expression of genes involved in inflammation and lipid metabolism, including ANGPTL4, and this was associated with increased tumor cell proliferation and invasion." (PMID 36074318, 2022). "Although several studies concluded that ANGPTL4 expression is associated with tumor progression and metastasis, many studies implicated ANGPTL4 in the inhibition of tumor angiogenesis and metastasis." (PMID 35366286, 2022). "The elevated ANGPTL4 expression in GCAFs was associated with tumor aggression characteristics, indicating a poor prognosis for GBCs patients." (PMID 34331381, 2021). "Mechanistically, ANGPTL4 induced activation of cancer-associated fibroblasts in the tumor microenvironment and promoted EMT in CRC cells through the ERK signaling pathway." (PMID 34405010, 2021). "Upregulation of ANGPTL4 is associated with a poor prognosis of cancers and promotes tumor cell proliferation and migration, including OS cells." (PMID 32563267, 2020). "A study showed that the tumor-facilitating effect of ANGPTL4 is strongly associated with PGE2 and hypoxia." (PMID 32928141, 2020).
tumor (continued). "Low expression of ANGPTL4 was significantly associated with advanced tumor stage, poor differentiation as well as poor overall and disease‐free survival (DFS) of HCC patients." (PMID 32410376, 2020). "Positive associations of ANGPTL-4 with IL-10 and IL-15 and IL-15 in the tumor and the mesenteric adipose tissue were observed in WSC group." (PMID 31741709, 2019). "On the other hand, in weight stable patients, who had a low ANGPTL-4 levels in plasma and tumor, it was observed an association of this protein to IL-10 and IL-15, anti-inflammatory and anti-tumorigenic factor." (PMID 31741709, 2019). "In WSC, we identified an association between the plasmatic ANGPTL-4, IL-15, and IL-10 in tumor and IL-15 in MES." (PMID 31741709, 2019). "ANGPTL-4 levels were higher in plasma and tumor of CC-group, and positively associated with pro-inflammatory and pro-tumorigenic factors." (PMID 31741709, 2019). "SR9243 also upregulated or downregulated genes associated with tumour proliferation, apoptosis, angiogenesis, invasion and migration, such as ANGPTL4, PDGFR, DUSP5, MMP7, FOXQ1 and MXD1 26–31." (PMID 31138790, 2019). "Tan and colleagues attempt to demonstrate the differences in the tumor characteristics and energy metabolism showing that mutational status of ANGPTL4 correlates on its ability to binding to integrin α5β1 leading to weaker activation of downstream signaling." (PMID 29389861, 2018). "ANGPTL4 is associated to angiogenesis, tumor cell motility and invasiveness cell migration, endothelial cell function, vascular leakage, neoangiogenesis and cell adhesion and motility interacting with matrix proteins." (PMID 29389861, 2018). "Microarray analysis identified ANGPTL4 as a crucial factor associated with the DATS-mediated anti-tumor effect in EJ cells." (PMID 28680385, 2017). "An analysis of recent studies makes it clear that the specific form of ANGPTL4 associated with the microenvironment tumour influences the clinical impact of this protein, along with other factors." (PMID 26508818, 2015). "The number of infiltrated tumor-associated macrophages (TAMs) stained by anti-CD68 antibody in xenograft liver tumor was significantly reduced after Ad-ANGPTL4 treatment." (PMID 25148701, 2014). "Conversely, ANGPTL4 is also implicated as a pro-angiogenic factor, and tumor-derived ANGPTL4 has been shown to promote metastasis by disrupting vascular integrity." (PMID 23925665, 2013). "Important molecules involved in the lipolysis, transport, and uptake of exogenous fatty acids include the fatty acid binding protein 4 (FABP4), the fatty acid tissue translocase CD36, and the angiopoietin-like protein 4 (ANGPTL4), which have all been recently implicated in tumor biology." (PMID 39456610, 2024). "Loss of ANGPTL4 led to significantly increased CAKi-1 tumor growth in immunocompromised mice." (PMID 39105498, 2024). "Lower expression levels of ANGPTL4 mRNA are significantly associated with advanced tumor stage, poor differentiation, tumor recurrence, and decreased post-operative overall and disease-free survival of HCC patients, thereby pointing to a tumor suppressive role of ANGPTL4." (PMID 36074318, 2022). "Emerging evidence supported that patients harbouring a higher level of ANGPTL4 in various types of tumour were associated with poor prognosis after radiotherapy, and ANGPTL4 was expected to be an attractive prognostic or predictive biomarkers and a novel target for cancer treatment." (PMID 36050447, 2022). "Recently, ANGPTL4 was detected in diverse tumor cells and associated with malignant phenotypes." (PMID 35461343, 2022). "Clinical studies have also found that ANGPTL4 expression is significantly associated with vascular and lymphatic invasion in human gastrointestinal tumors, further highlighting the role of ANGPTL4 in tumor metastasis." (PMID 34331381, 2021).
tumor (continued). "Consequently, the expression of CA9, NDUFA4L2, EGLN3, BHLHE41, VWF, IGFBP3, and ANGPTL4 is associated with ccRCC tumor progression and decreases at stage 4 after initial growth relative to normal tissues." (PMID 34046336, 2021). "Also, plasma ANGPTL-4 level was positively associated with IL-10 and IL-15 contents in tumor and with IL-15 content in mesenteric adipose tissue." (PMID 31741709, 2019). "A positive association was verified between plasmatic ANGPTL-4 and NFκB levels in tumor from CC." (PMID 31741709, 2019). "However, in tumor models of endothelial cells and mice, Angptl4 caused endothelial barrier damage by integrin signaling and disruption of intercellular VE-cadherin and claudin-5 clusters." (PMID 29912977, 2018). "ANGPTL4 deficiency reduced IC50 of anti-tumor drugs and enhanced apoptosis of cancer cells." (PMID 30342537, 2018). "It was shown that downregulation of ANGPTL4 simultaneously with upregulation of fibronectin 1 (FN1) might be implicated in anti-tumor activity of U94, an oncosuppressor, in androgen resistant prostate cancer cell lines." (PMID 29389861, 2018). "Multiple physiological and pathological roles associated with osteolytic disease are ascribed to ANGPTL4 including promotion of osteoclast-mediated bone resorption, cartilage degradation, angiogenesis and vascular permeability, as well as tumour cell growth and metastasis." (PMID 28458654, 2017). "A recent study demonstrated that the overexpression of Angptl4 impairs tumor growth associated with enhanced apoptosis, and plays a role in the inflammatory response; however, the mechanisms involved remain unknown." (PMID 23783408, 2013). "The results revealed that the upregulation of ANGPTL4 and Follistatin were significantly and positively associated with the extent of tumor regression, indicating that these proteins may serve as functional biomarkers linking propranolol exposure to therapeutic response." (PMID 41487524, 2025). "Therefore, Angptl4 produced from other, non-tumor cell tissues in the mouse, may cause more variation in the results." (PMID 31602400, 2019). "Second, inhibiting ANGPTL4 in vivo decreased IL1A production and tumor initiation, the two probably being functionally linked as inhibiting IL1A slows down RAS‐dependent tumor initiation in a pancreatic model." (PMID 41347893, 2026). "Evaluation of the contribution of some immune cells, such as neutrophils, which can be regulated by ANGPTL4 and senescent cells and impact tumor initiation, will also be required." (PMID 41347893, 2026). "In fact, ANGPTL4 exhibited a tumor suppressive effect in VHL WT tumors by inhibiting lysosomal acid lipase." (PMID 40233044, 2025). "On the other hand, the CTRP database’s top correlated drugs showed that increased ANGPTL4 expression conferred tumor resistance to commonly used chemotherapeutics such as chlorambucil, doxorubicin, and vincristine." (PMID 40233044, 2025). "Overall, our study demonstrates that ANGPTL4 exerts a detrimental impact at the genomic level by influencing tumor migration, EMT, cell-cell communication within the TME, and immune infiltration." (PMID 40233044, 2025). "The C-fragment of ANGPTL4 (cANGPTL4) has been shown to possess multiple pro-tumorigenic activities such as promoting metastasis, tumor growth, and facilitating angiogenesis." (PMID 40233044, 2025). "Within the tumor microenvironment, conditions such as hypoxia and nutrient deprivation can exacerbate cellular stress, leading to dysregulated expression of ANGPTL4 and GCN1." (PMID 41011152, 2025). "On the other hand, the n-fragment of ANGPTL4 (nANGPTL4) has been shown to inhibit metastasis and tumor growth." (PMID 40233044, 2025). "They identified FSCN1 as a positive regulator of the angiogenic factor ANGPTL4, linking it to tumor angiogenesis." (PMID 41148856, 2025).
tumor (continued). "ANGPTL4 plays a significant role in tumor progression via its positive regulation of EMT and angiogenesis, while possibly harboring a TGF-B dependent role in systemic metastasis." (PMID 40233044, 2025). "Our research demonstrates that D-2HG-induced m6A modification of ANGPTL4 exerts a dual effect: it not only promotes tumor cell proliferation and metastasis but also modulates macrophage polarization within TME." (PMID 39910592, 2025). "In summary, D-2HG-mediated secretion of ANGPTL4 promotes M2 polarization of tumor-associated macrophages in the TME, inhibiting the anti-tumor immune responses and promoting TNBC growth and metastasis." (PMID 39910592, 2025). "Accordingly, ANGPTL4 has been shown to play central roles in multiple cancer types, but with widely varying functions and outcomes—ranging from anti-tumor to metastatic and oncogenic effects." (PMID 40723247, 2025). "In our study, we identified that D-2HG accumulation inhibited the activity of FTO, leading to increased m6A modification of ANGPTL4, a protein known to promote tumor progression and metastasis." (PMID 39910592, 2025). "This has led to a lack of conclusive evidence and has led some researchers to postulate a conflicting role for ANGPTL4 in tumor biology." (PMID 40233044, 2025). "Likely due to the greater sequencing read depth, patient 1,010,020 had a substantially greater number of such genes—a total of 187; these likewise included several tumor suppressor genes, such as ANGPTL4, ARHGEF10, MARVELD1, and SQSTM1." (PMID 41428220, 2025). "This corroborates the fact that ANGPTL4 is an important signaling protein between tumor cells and its stromal environment, facilitating many of the detrimental effects of cancer." (PMID 40233044, 2025). "Among the 13 ferroptosis- and lipid metabolism–related signature genes, CPA3, DAPK1, and ANGPTL4 exhibited significant positive correlations with most immune checkpoint genes, suggesting that higher expression of these genes may be associated with an immune-activated tumor microenvironment." (PMID 41425595, 2025). "ANGPTL4 overexpression has been detected in many human tumor cells; it is mainly secreted by proliferating tumor epithelial cells, and stimulates the downstream ERK pathway through interaction with specific integrins and extracellular matrix proteins." (PMID 38311733, 2024). "Pan-cancer cells often exhibit elevated levels of ANGPTL4, a protein that interacts with integrins to generate O2−, significantly contributing to tumor growth and survival." (PMID 38694500, 2024). "Studies indicate the presence of multiple hypoxia-related tumor microenvironment cell subpopulations in ccRCC, with ANGPTL4+ endothelial cells potentially playing a pivotal role in tumor angiogenesis, indicating significant prognostic value." (PMID 39840089, 2024). "Using several ccRCC tumor models, we demonstrate a tumor-suppressive role of ANGPTL4 in a subset of RCC cells mainly due to its novel function in regulating lysosomal acid lipase (LAL) within cancer cells." (PMID 39105498, 2024). "Current research suggests that ANGPTL4 primarily fuels tumor progression and metastasis through its C-terminal fragment." (PMID 38683136, 2024). "While FABP4 expression was comparable between the groups, we observed higher expression levels of CD36 and ANGPTL4 in tumor cells at the invasive front in overweight/obese TNBC patients." (PMID 39456610, 2024). "Renca-A4 cells had significantly decreased tumor growth compared to control Renca cells, further supporting the tumor suppressive function of ANGPTL4 in RCC." (PMID 39105498, 2024). "ANGPTL4 plays pivotal roles in regulating glucose homeostasis and lipid metabolism, and thereby affects the invasion and chemotherapy resistance of tumor cells." (PMID 38643448, 2024).
tumor (continued). "To further understand which ANGPTL4 signaling peptide suppresses tumor growth, we treated the CAKi-1 tumor–bearing mice with a cANGPTL4 blocking antibody, which we have previously shown inhibits cANGPTL4-mediated angiogenesis both in vitro and in vivo." (PMID 39105498, 2024). "In disease prognostic models, ANGPTL4 has demonstrated diagnostic potential, with an AUC of 0.7665, and its expression in RCC tumor samples is significantly greater than that in normal kidney tissue." (PMID 39840089, 2024). "In ccRCC tumor tissues, ANGPTL4 expression is also significantly elevated, suggesting a potential role for ANGPTL4 in ccRCC." (PMID 39840089, 2024). "To understand the molecular mechanism of ANGPTL4 in suppressing tumor growth, we performed RNA-seq analysis on the ccRCC cell lines with ANGPTL4 KO." (PMID 39105498, 2024). "In fact, elevated STC1 in conjunction with angiopoietin-like 4 (ANGPTL4) directly modulates the tumor microenvironment, enhancing aggressive OvCa progression." (PMID 39186548, 2024). "Cancer-associated fibroblasts signal to the cancer cells for tumour growth and angiogenesis via pathways such as HGF, ANGPTL4, HBEGF and FGF." (PMID 39149248, 2024). "In our animal experiments, we established that ANGPTL4 significantly suppresses tumor growth in human CAKi-1 and mouse Renca RCC cells with WT VHL." (PMID 39105498, 2024). "Knocking down ANGPTL4 led to inhibited tumor metastasis and energy metabolism in mouse models, with minimal effects on glycolysis." (PMID 39090094, 2024). "These molecular functions of ESM1/ANGPTL4 significantly promote angiogenesis in the OC tumor microenvironment." (PMID 38212795, 2024). "Loss of ANGPTL4 resulted in a decrease in the number of CD31+ endothelial cells, indicating reduced tumor vascularization." (PMID 39105498, 2024). "Meanwhile, hypoxic tumour cell-derived exosomal miR-340-5p and angiopoietin-like 4 (ANGPTL4) were evidenced to confer radioresistance in ESCC and NSCLC by targeting KLF10/UV radiation resistance-associated gene (UVRAG) and inhibiting ferroptosis, respectively." (PMID 38802766, 2024). "To confirm the functional role of ANGPTL4 in suppressing tumor growth, we performed a series of in vitro experiments on A4KO and WT ccRCC cells." (PMID 39105498, 2024). "ANGPTL4 confers anoikis resistance, a property that supports survival of tumor cells when they lose adhesion during the metastatic process." (PMID 38886396, 2024). "Further studies indicate that ANGPTL4 suppresses ccRCC tumor growth possibly via inhibiting cancer cell intrinsic LAL." (PMID 39105498, 2024). "RT-qPCR was first used to examine ANGPTL4 transcription in 17 matched OC and tumor-adjacent tissue specimens from patients in our hospital." (PMID 38311733, 2024). "The loss of ANGPTL4 in ccRCC cell lines results in increased tumor growth and colony formation in a lysosomal acid lipase (LAL)-dependent manner, a phenotype rescued by the expression of N-terminus ANGPTL4." (PMID 39105498, 2024). "Binding of ANGPTL4 to endothelial cells disrupts their connectivity, increases pulmonary capillary permeability, and promotes vascular endothelial migration of tumor cells." (PMID 38887298, 2024). "Most evidence points toward ANGPTL4 primarily acting as a tumor promoter, disrupting vascular tight junctions and increasing the capillary permeability, and facilitating vascularizing on which malignant cells are highly dependent." (PMID 37688629, 2023). "ANGPTL4 is a known angiogenic factor that can be directly induced by HIF-1α in tumor cells under hypoxic conditions, and its expression is significantly increased in BC patients." (PMID 37138324, 2023). "We examined the expression of ANGPTL4 in different cell types and found that it was significantly expressed in epithelial (tumor) cells and to a lesser extent in some stromal cells." (PMID 37138324, 2023).